APP (amyloid beta precursor protein)
Diseases named in the same sentence as APP in open-access papers (continued):
Sharing a sentence is not in itself a finding about the gene and the disease.
amyloid (continued). "In support of a direct HCRT effect on Aβ homeostasis, there is evidence that HCRT has direct effects on both microglial phagocytosis of Aβ and on amyloid precursor protein (APP) processing in the hippocampus that support roles for HCRT in amyloid dyshomeostasis." (PMID 36275002, 2022). "However, when investigating the ratio of microglia counts-to-proximal amyloid plaque area in the hippocampus of APP/PS1 animals, a significant reduction in the ratio was examined in treated animals (p = 0.015)." (PMID 35314754, 2022). "Therefore, we generated APP/PS1/Sirt3-/- mouse as a model for comorbid AD with amyloid pathology and MetS." (PMID 36396721, 2022). "We conclude that our new Cre-inducible models express transgenic APP at levels comparable to other amyloid mouse strains and that amyloid onset in each model is dictated by the combination of expression levels, the presence or absence of mutant presenilin and the specific APP mutations encoded." (PMID 35394029, 2022). "Similarly to AD patients, expression of CXCR4 gene is upregulated in brains of rTg4510 murine model of tauopathy and APP/PS1 model of amyloidosis." (PMID 35821178, 2022). "These mice express the mutated APP and TAU human genes in the brain, and closely recapitulate the human amyloid and TAU pathology, including cognitive deficits and the alteration in exploratory and anxiety-like behavior, fear learning and inflexibility in hippocampus-dependent learning." (PMID 35628609, 2022). "Here, we argued that fully matured SC-CA1 synapses in adult animals might need stronger STDP paradigms for robust t-LTP, and that this t-LTP might be more sensitive to amyloidosis pathology in APP/PS1 than the low repeat protocols." (PMID 33573114, 2021). "To investigate whether the behavioral improvement in APP/PS1/FTnKO mice was accompanied by any changes in neuropathology, we assessed cerebral amyloid load and associated neuroinflammation." (PMID 34315531, 2021). "In addition to the parenchymal Aβ plaques, cerebral amyloid angiopathy (CAA) is also observed in different amyloidosis animal models, especially in the APPDutch mice, Tg-SwDI, APP/London, APP23, arcAβ, and APPswe mice." (PMID 34832961, 2021). "APP is best known as the precursor molecule that, after cleavage by β-secretase and γ-secretase, produces 37–49 amino acid residue Aβ peptides, which are the primary component of the amyloid plaques found in the brains of people with AD." (PMID 34959925, 2021). "Stalled APP.C99 species with C-terminal extensions (CAT-tails) resulting from inadequate RQC are prone to aggregation, causing endolysosomal and autophagy defects and seeding the aggregation of amyloid β peptides, the main component of amyloid plaques." (PMID 34663454, 2021). "Notably, our previous work comparing the TfRMAb-TNFR and etanercept at a twofold higher dose (3 mg/kg) showed more robust effects of the TfRMAb-TNFR than etanercept in the male APP/PS1 mouse model of amyloidosis." (PMID 34972522, 2021). "The amyloid hypothesis proposes that amyloid plaques formed by aggregates of the Aβ peptide generated by proteolytic cleavage of amyloid precursor protein (APP) are central to AD pathology." (PMID 34289882, 2021). "APP/PS1 mice treated with intraperitoneal memantine injections of 10 mg/kg for 4 months also revealed significantly reduced amyloid plaque burden in cortex and hippocampus at the age of 7 months, together with significant improvements in a novel object recognition task test of short-term memory." (PMID 32914393, 2021). "It is well known that GSK-3β is a proline-directed serine/threonine kinase with structural activity, which enhances tau phosphorylation and regulates the amyloidosis of APP by regulating the expression of BACE and the function of gamma-secretase in vivo and in vitro." (PMID 34987593, 2021).
amyloid (continued). "In the present study, an examination of the physiological significance of AICD SUMOylation disclosed that transduction of lenti-FLAG-AICDWT vector to the hippocampus of APP/PS1 mice decreases the amount of Aβ and amyloid plaques and rescues spatial memory deficit in APP/PS1 mice." (PMID 32950104, 2021). "Thus, the TAPS mice had an amyloidosis phenotype combining the distribution patterns from both the APP/PS1 and TBA2.1 mice, but with earlier onset and faster progression." (PMID 34209113, 2021). "Amyloidosis, which is implicated in cerebral amyloid angiopathy and AD, is reflected by aberrant cleavage of the full-length APP by BACE1 resulting in the production of soluble APP fragment and a membrane-bound CTF." (PMID 34027891, 2021). "In addition, strong, early microglial effects were observed using amyloidosis mouse models, different from the APP/PS1 model used here." (PMID 34202490, 2021). "Notably, in the APP/PS1 model, the selective prevention of the conversion of microglia to DAM, via proliferation, caused a significant prevention of the amyloid pathology, evidenced by a reduction in the density of Aβ plaques and total Aβ load." (PMID 34107254, 2021). "We thus explored whether PBM improves cognitive and memory deficits in APP/PS1 mice via reducing cerebral amyloid pathology." (PMID 34493703, 2021). "They participate in the metabolism of amyloid precursor protein (APP) that forms amyloid plaques." (PMID 34889159, 2021). "Amyloid plaques are accumulations of abnormally folded amyloid β peptides (Aβ) generated from the sequential proteolytic cleavage of amyloid precursor protein (APP) by β- and γ-secretase." (PMID 34564432, 2021). "In addition, we found that, compared with WT AICD, SUMOylated AICD exerts greater effects in reducing Aβ level and amyloid plaque accumulation and in rescuing the spatial memory deficit in APP/PS1 mice." (PMID 32950104, 2021). "Indeed, total amyloid plaque loads increased in both cortex (53%) and hippocampus (p < 0.05) of APP/PS1/Aβ-Th1 mice compared to those of untreated APP/PS1 mice." (PMID 34798897, 2021). "We have identified marked sex-related differences in microglial activation, morphology, metabolism and function in APP/PS1 mice and we propose that these linked changes contribute to the more marked amyloid pathology, reduced neuroprotection and more profound cognitive impairment in females." (PMID 34112929, 2021). "In conclusion, our results provide new insights into the function of NOB to modulate circadian rhythms and physiology, which may contribute to the observed beneficial effect on amyloid pathology in female APP/PS1 mice." (PMID 34356628, 2021). "They crossed SIRT3−/− mice with APP/PSI mice (double-transgenic mouse models of AD expressing a chimeric mouse/human amyloid precursor protein and containing the L166P mutation, both directed to the CNS) and generated APP/PS1/SIRT3−/− mice with metabolic syndrome and amyloid pathology." (PMID 33669988, 2021). "In AD, build-up of toxic β-amyloid (Aβ) is known to promote formation of amyloid plaques, and that accumulation of Aβ involves proteolytic processing of amyloid precursor protein (APP), with specific generation of the toxic forms of Aβ driven by sequential β- and γ-secretase cleavage of APP." (PMID 33440796, 2021). "Abnormal mitochondrial distribution and round, swollen, and damaged mitochondria were also documented, coinciding with the loss of mitochondrial oxidative activity but preceding the onset of amyloid plaque formation and memory impairment in Tg2576 APP transgenic mice and APP/PS1 mice." (PMID 34063708, 2021). "Treatment of 5xFAD mice, which develop prominent amyloid pathology, with the same paradigm also rescued behavioral deficits but did not affect extracellular amyloid-β (Aβ) levels or amyloid precursor protein (APP) processing." (PMID 34913091, 2021).
amyloid (continued). "On the contrary, in 3xTg-AD mouse model containing mutations not only in APP but also in tau protein and presenilin, we did not detect any gender-related difference in amyloid load, the ECS diffusion parameters, or in astrocyte swelling." (PMID 35153718, 2021). "Moreover, synergistic effects of TRL-Aβ with exaggerated central nervous system (CNS) synthesis of human Aβ are also suggested by the findings of accelerated amyloidosis in amyloid precursor protein/presenilin 1 (APP/PS1) mice maintained on atherogenic diets." (PMID 34520451, 2021). "However, reduced Ragulator-Rag complex in APP mice with Arg1 insufficiency during amyloidosis indicated that arginine metabolism has an unappreciated role in executing this function at the level of the lysosome." (PMID 33519806, 2020). "To test whether LEO can exert anti-amyloid effects, we treated APP/PS1 mice starting at 8 months of age with daily LEO inhalation over a period of 30 days." (PMID 32392535, 2020). "Moreover, we found that the differences in bacterial taxa between the WT and APP/PS1 mice increased with age, specifically at 6 and 9 months, which coincides with the progression of amyloid plaque formation and microglial activation in the APP/PS1 mouse brain." (PMID 32596386, 2020). "Furthermore, the amyloid burden at the molecular layer of hippocampal dentate gyrus was significantly smaller in the double tg mice by ~ 76% (mean values: 17.6% in APP and 4.30% in double tg mice)." (PMID 33287899, 2020). "To determine whether intranasal delivery of 9-cis RA affects amyloid pathology, we treated 6-month-old APP/PS1 mice for a period of 4 weeks, as these mice are known to develop amyloid plaques at 5 to 6 months." (PMID 32209731, 2020). "Reduces inflammation and attenuates amyloidosis in the hippocampus in PS1/APP transgenic mice." (PMID 32765225, 2020). "In summary, the current investigation demonstrates that a food flavoring CFA, when given during early stages of AD-related processes, could greatly diminish amyloid pathogenesis in APP/PS1 transgenic mice." (PMID 31903114, 2020). "APP plays a central role in the onset and progression of the amyloid pathology found in AD." (PMID 32327470, 2020). "In a study by Chen and colleagues, transgenic APP/PS1 mice, a model bearing the mutations in transgenes for APP and PSEN1 resulting in Aβ plaque deposition, demonstrated altered microbiota preceding amyloidosis and microgliosis, suggesting a role of the gut microbiota in AD pathogenesis." (PMID 33153085, 2020). "Furthermore, our results suggest the effect of Trem2 deletion on Apoe expression is apparent only in APP mice and depends on the amyloid deposition." (PMID 32703241, 2020). "Pet imaging studies showed that amyloid related signals can be found in the cortex, hippocampus, and striatum of the 6-month-old APP/PS1 mice and are easily recognizable in the 9-month-old APP/PS1 mice, suggesting that the Aβ symptom become significant with increasing age." (PMID 32423012, 2020). "Especially, the amyloid burden at the molecular layer of hippocampal dentate gyrus, where diffuse-type plaques were predominant, was significantly smaller in the double tg mice by ~ 41% at 15 M (mean values: 36.4% in APP and 21.7% in double tg mice)." (PMID 33287899, 2020). "The amyloid hypothesis has been the prevailing theory for sporadic AD (SAD) pathogenesis since the discovery of APP gene involvement in familial AD and Down syndrome." (PMID 32457796, 2020). "Ca2+ dysregulation and altered APP processing, the two major hits linked to PS2-N141I expression, could affect neural circuit dynamics during the progression of amyloidosis." (PMID 32992716, 2020). "With regards to EV secretion, intercellular transport of APP or the β-secretase derived catabolites likely has a harmful effect on naïve neurons, while inhibition of EV release may result in decreased amyloid plaque load present in AD mouse models." (PMID 32731849, 2020).
amyloid (continued). "Since abundant gliosis is associated with the presence of amyloid pathology, we next assessed whether CLU overexpression had a differential effect on inflammatory changes in APP/PS1 mice." (PMID 33246484, 2020). "In our study, APP/Arg1 insufficient mice showed increased CD68 expression in HPC and ECX compared to APP/Arg1 sufficient mice and nTg/Arg1 insufficient mice, suggesting that amyloidosis and Arg1 deficiency promoted CD68 expression." (PMID 33519806, 2020). "Metabolomic results from APP/PS1 mouse models revealed that the liver was the organ first affected during the progression of amyloid pathology, demonstrating impaired energy metabolism, amino acid metabolism, nucleic acid metabolism, as well as ketone and fatty acid metabolism." (PMID 32812166, 2020). "Consistently, two groups demonstrated the rescue effects of DLP1 inhibitor midivi-1 on mitochondria morphology and movements at early stage in APP transgenic mice which alleviated amyloid pathology likely through reducing Aβ production and improved cognitive deficits." (PMID 32471464, 2020). "The increased levels of Hsf1/B2 RNA processing in APP 6-month-old mice raised the question whether response to amyloid toxicity in hippocampal cells is connected with an Hsf1-mediated increase in B2 RNA processing." (PMID 33191914, 2020). "Thus, doubling the frequency of slow oscillations, increased amyloid plaque load in the cortices of APP mice." (PMID 31221985, 2019). "However, levels of most phospholipid species in PS1/APP mice were nominal in the hippocampus, while in the cortex, levels were significantly decreased at ages post-onset of amyloid pathology." (PMID 30837829, 2019). "Imaging studies have shown that APP/PS1 mice aged 6–8 weeks can develop amyloidosis in the brain." (PMID 31485251, 2019). "The idea of impaired long-range functional connectivity in amyloid plaque bearing transgenic mice is further supported by an in vivo calcium imaging study employing another APP/PS1 model (APP23 × PS45) with a similar time course of amyloid accumulation as the APPswe/PS1dE9 mouse." (PMID 30926900, 2019). "In addition, it has been reported that female APP/PS1 mice are more likely to produce amyloidosis at a young age than males, and this resembles the fact that the incidence of AD in women is higher than in men." (PMID 31485251, 2019). "These proteins have a one-way transmembrane domain, but only APP produces amyloidosis fragments." (PMID 31534855, 2019). "Furthermore, we confirmed the molecular mechanisms for it and ROCK1 inhibition decreased amyloid plaque formation in the brain of APP/PS1 mice and prevented APP‐CTF aggregation in the surrounding halo of amyloid plaques." (PMID 31287605, 2019). "Additionally, lentiviral overexpression of miR-181a via intrahippocampal injection ameliorates cognitive deficits and amyloid plaque deposition in APP/PS1 mice, indicating a beneficial role of miR-181a against AD progression." (PMID 31467256, 2019). "Interestingly, 17,18-DiHETE is also increased in the brains of APP/tau mice, which exhibit amyloid pathology." (PMID 31491971, 2019). "Furthermore, the accumulation of amyloid in the cerebellum differentially affected males and females of the APP/PS1 transgenic line, which was found to be tenfold higher in 15-month-old females." (PMID 31010414, 2019). "Moreover, blockade of APP Ser655 phosphorylation, or inhibition of ROCK1 activity with either shRNA knockdown or Y‐27632, ameliorated amyloid pathology and improved learning and memory in APP/PS1 mice." (PMID 31287605, 2019). "CD33-deficient Amyloid precursor protein (APP)/Presenilin 1 (PS1) mice showed reduced amyloid pathology compared to age-matched wildtype (WT) controls, supporting the idea that reduced microglial CD33 function is beneficial with respect to amyloid pathology." (PMID 31507408, 2019).
amyloid (continued). "The results above suggest that the inhibition of the Nogo/NgR pathway promotes microglial recruitment to the Aβ plaques and expression of key phagocytosis receptor and might further increased clearance of amyloid load in APP/PS1 mice." (PMID 30029608, 2018). "Similarly, BACE1 accumulates in swollen dystrophic neurites in very close proximity to amyloid plaques in the brain of APP transgenic mice and AD patients, suggesting that Aβ toxicity results in BACE1 elevation." (PMID 29391027, 2018). "Here we assess the possibility that, in the 5XFAD mouse model, overexpression of APP and PS1 transgenes leads to ER stress and activation of the UPR and that this could be the cause of phenotypes attributed to high levels of amyloid pathology." (PMID 30315100, 2018). "Dysregulated energy homeostasis including hyperphagia and exacerbated obesity was elicited prior to the presence of the amyloid pathology in the hypothalamus of HFD APP/PS1 transgenic mice; nevertheless, cortical neuroinflammation and the level of serum Aβ and IL-6 were significantly elevated." (PMID 30096853, 2018). "Thus, daily oral treatment with DA-9803 halted plaque deposition and led to a reduction in amyloid plaque number and amyloid plaque burden in APP/PS1 mice over the 2-month period." (PMID 29378621, 2018). "By using the APP/PS1 transgenic mouse (a rapidly progressing amyloidosis model), we have previously shown that extensive amyloidosis increases the DK metrics in the cortex and thalamus of 16-month-old APP/PS1 mice as compared with age-matched wild-type (WT) mice." (PMID 29370870, 2018). "In this context, it is important to emphasize that APPPS1 mice overexpress human APP with the Swedish mutation, which is more efficiently cleaved by BACE1 than wild type APP, which results in an aggressive model of early-onset amyloid pathology." (PMID 29327084, 2018). "Thus, to understand the development of amyloid pathology in the context of chromosome 21 trisomy we work with a widely-used transgenic APP mouse model." (PMID 29945247, 2018). "In APP/PS1 transgenic mice, TNFR1 deficiency ameliorated amyloidosis." (PMID 29472246, 2018). "Because mice do not naturally develop amyloid pathology, multiple mouse models that overexpress various forms of APP and PS1 with mutations that cause autosomal dominant AD (ADAD) have been developed to study amyloidogenesis in tractable animal model systems." (PMID 30315100, 2018). "Transgenic mouse models have been instrumental to study amyloidosis, but observations might have been confounded by APP-overexpression artifacts." (PMID 29674739, 2018). "SOCS3 reduces GFAP and STAT3 expression in APP mice, even around amyloid plaques (star)." (PMID 30322407, 2018). "Indeed, the intracerebroventricular infusion of BMP9 has recently been demonstrated to counteract the cholinergic defects and reduce amyloidosis in APP.PS1/CHGFP mice." (PMID 28228716, 2017). "Our results also demonstrate that inhibition of HDAC3 in the hippocampus of APP/PS1 mice decreases Aβ levels and alleviates amyloid plaque formation, which might be associated with decreased PS‐1 levels." (PMID 28771976, 2017). "Here, we demonstrate that a 4-week intranasal BMP9 treatment reduced both the amyloid plaque load and Aβ levels, inhibited tau hyperphosphorylation, suppressed neuroinflammation, and finally reversed the cognitive impairments in APPswe/PSEN1dE9 (APP/PS1) mice." (PMID 28228716, 2017). "Based on the fact that YXQN extract supplementation may ameliorate cognitive decline in the AD mouse model, we next investigated the core pathology of the AD-amyloid burden in APP/PS1 mice of each group." (PMID 28603494, 2017). "The 3xTg-AD mouse is a triple-transgenic mouse model for AD harbouring PS1-M146V, APP(Swe) and tau-P301L transgenes that exhibit an age-related neuropathological progression pattern and comprises both amyloidosis and tau pathology and develops plaques and tangles." (PMID 29261717, 2017).